INS (insulin)
Diseases named in the same sentence as INS in open-access papers (continued):
Sharing a sentence is not in itself a finding about the gene and the disease.
Hypoglycemia (continued). "Because they briefly stimulate insulin secretion, which can reduce the risk of hypoglycemia, meglitinides are especially good for people with hepatic or renal impairment and elderly patients." (PMID 35252271, 2022). "Insulin use carries a high risk of hypoglycemia, also favored by portosystemic shunting; in cases treated by β-blockers, the risk is complicated by hypoglycemia unawareness, increasing the likelihood of brain damage." (PMID 34172646, 2022). "The impaired glycaemic control during hospitalization is usually treated with short acting insulin many times per day, which represents a time-consuming task for nurses and is most likely associated with a risk of high glycaemic variability and hypoglycaemia." (PMID 35162066, 2022). "The identical rates of hypoglycemia development after insulin injection in control and mutated mice also indicated that insulin sensitivity was not modified by Agpat5 inactivation in AgRP neurons." (PMID 36180454, 2022). "In order to reduce the risk of hypoglycemia, it is necessary to educate the patient about risk factors, dosage, insulin supply, and glycemic monitoring." (PMID 35324747, 2022). "Despite the absence of additional risk factors, patients receiving intensive insulin therapy are at increased risk of hypoglycemia." (PMID 36318542, 2022). "We also found that drug regimens, especially insulin and sulfonylurea, were associated with an increased risk of hypoglycemia in older patients with AD and T2DM." (PMID 35055382, 2022). "Insulin was the second most common medication associated with ED visits in older people ≥ 65 years, due to hypoglycemia." (PMID 35831938, 2022). "Incretin mimetics have potent hypoglycemic effects with lower risk of hypoglycemia and can be regarded as alternatives for insulin." (PMID 36142794, 2022). "One of the reasons for the ineffectiveness or worsening of the risk for dementia with insulin or sulfonylurea use is the higher risk of hypoglycemia." (PMID 35742986, 2022). "The course of hypoglycemia caused by insulin overdose also depends on other factors, such as body weight, amount of body fat, and liver function." (PMID 35324747, 2022). "Daily insulin dose was analyzed to determine the association with risk factors such as the occurrence of hypoglycemia." (PMID 36494830, 2022). "Hypoglycemia is frequently associated with insulin therapy in diabetic patients; it leads to many short and long-term complications and even death if not addressed in time." (PMID 35178205, 2022). "Other determinants influencing insulin therapeutic adherence have been identified in the literature such as quality of life, understanding of the risk of hypoglycemia, and changing injection material." (PMID 35573427, 2022). "Overall, insulin analogs appear to have a lower risk of hypoglycemia and better postprandial control compared to human insulin." (PMID 35690830, 2022). "Other causes of hypoglycemia were also excluded upon admission, namely exogenous insulin and oral hypoglycemic agent administration, as well as insulin autoimmune syndrome (Hirata disease), as insulin autoantibodies were negative." (PMID 35838801, 2022). "The intranasal route also prevents the risk of peripheral hypoglycaemia, which is associated with the chronic administration of insulin." (PMID 36555450, 2022). "ABA supplementation in conjunction with insulin holds the promise of reducing the dose of insulin required in T1D, reducing the risk of hypoglycemia, and improving muscle insulin sensitivity and glucose consumption." (PMID 35736456, 2022). "Decreasing the usual at home rapid insulin dose by 20–30%, especially in those who have decreased appetite, decreases the risk of hypoglycemia." (PMID 35246230, 2022). "The increased risk of hypoglycemia and reduced insulin clearance make the application of insulin in patients with advanced DKD still controversial." (PMID 36142794, 2022).
Hypoglycemia (continued). "Compared with insulin and sulfonylurea, metformin has stronger beneficial effects possibly because of the lower risk of hypoglycemia." (PMID 35337110, 2022). "Future randomised trials should focus on identifying the optimal regimen of insulin therapy to mitigate the risk of hypoglycaemia." (PMID 35552566, 2022). "In extreme cases, insulin overdose causes severe hypoglycemia resulting in loss of consciousness, coma, severe and irreversible brain injuries, or death." (PMID 35324747, 2022). "Patients with T1DM often consciously elevate pre-exercise glucose levels to combat the risk of hypoglycemia by excessively decreasing insulin and subsequently compromising glycemia through carbohydrate intake." (PMID 36083870, 2022). "The use of insulin or sulphonylureas was associated with the highest risks, likely due to the increased risk of hypoglycemia induced by these treatments." (PMID 36060943, 2022). "The insulin hypoglycemic program has been recognized as the main risk factor of hypoglycemia, which was also shown in our study." (PMID 35538461, 2022). "Conversely, at the end of the event when the swimmer is rewarmed, there is a risk of increased insulin absorption at a time when there is already a high risk of hypoglycaemia related to prolonged exertion." (PMID 36425473, 2022). "This protocol highlights the powerful application of an internet-based panel survey to assess long-term hypoglycemia risk in a large, community-based cohort of adult Americans with insulin- and/or secretagogue-treated T1DM and T2DM." (PMID 35025756, 2022). "There is a great risk of hypoglycemia because of reduced renal gluconeogenesis, reduced renal clearance and degradation of insulin, increased glucose uptake in dialysis, impaired hormonal counter-regulation, and nutritional deprivation." (PMID 35690830, 2022). "Insulin is considered first-line pharmacotherapy but is associated with hypoglycaemia, excessive gestational weight gain (GWG) and an increased caesarean delivery rate." (PMID 36131291, 2022). "The risk of hypoglycemia is higher with human insulin than with analog insulin such as Lantus and Novorapid, and therefore the preferred type of insulin in T1DM is analog insulin." (PMID 35858952, 2022). "We noted that the patient experienced continuous weight gain after having IAs and hypoglycaemia, which is possibly caused by the anabolic effects of insulin." (PMID 36440205, 2022). "Basal insulin treatment has a lower risk of hypoglycaemia, which enables more aggressive treatment and is easier to use with less variation." (PMID 35574003, 2022). "The lower prevalence of clinically significant biochemical hypoglycemia and the decrease in the required dose of insulin during pregnancy were associated with increased endogenous insulin secretion." (PMID 35207323, 2022). "As hypoglycemia is a risk factor in these mice, blood insulin and glucose served as prognostic biomarkers." (PMID 35118189, 2022). "The safety and efficacy of this drug in T2DM patients were evaluated in the DUAL program, in DUAL V study it was compared with basal insulin alone, finding a significant decrease in HbA1c and additionally weight loss and lower risk of hypoglycemia." (PMID 35573995, 2022). "From the point of view of forensic science, it is essential to analyze the acts performed in a state of limited consciousness, which is a result of hypoglycemia caused by insulin abuse and overdose." (PMID 35324747, 2022). "Because excessive doses of exogenous free INS can cause hypoglycemia, a purification step is necessary." (PMID 36296745, 2022). "For these respondents, access to healthy foods is a challenge, which is a risk factor for hypoglycaemia if the participant injects insulin." (PMID 36425875, 2022). "By favoring glucose excretion in the urines, SGLT-2Is reduce blood glucose levels by an insulin-independent mechanism, with nearly null risk of hypoglycemia." (PMID 34172646, 2022).
Hypoglycemia (continued). "This 27-year-old female had underlying Graves’ disease and presented with hypoglycemia and a high insulin but normal C peptide level after taking MTZ." (PMID 35758364, 2022). "Further decreases in insulin were observed at day 108 in response to a small increase in CGM readings <70 mg/dL to minimize the risk of hypoglycemia." (PMID 35147501, 2022). "In fact, when a GLP-1 RA is added to basal insulin, the combination is as effective as an intensified insulin regime in terms of HbA1c control, but with a much lower risk of hypoglycaemia and weight gain." (PMID 33466656, 2021). "DCCT also showed that retention of residual endogenous insulin secretion (defined by residual C-peptide secretion) was associated with a lower frequency of hypoglycemia and microvascular complications, including nephropathy." (PMID 34054721, 2021). "MR1704, a GPR40 agonist, improved glucose homeostasis through glucose-dependent insulin secretion (GSIS) with a low risk of hypoglycemia and pancreatic toxicity in the GK rats." (PMID 34943862, 2021). "SGLT2i used as a monotherapy are all associated with a low risk of developing hypoglycaemia, and hypoglycaemia risk is raised when utilised as an add-on therapy with sulfonylurea or insulin." (PMID 34497814, 2021). "Even though the glycemic target adjustment is not part of the proposed algorithm to determine the patient’s basal insulin needs, it was added to the closed loop controller to minimize the risk of hypoglycemia." (PMID 34372462, 2021). "In particular, while all strategies can substantially reduce the risk of acute hypoglycemia, prolonged changes in insulin sensitivity would require additional insulin bolus adjustment for meals following exercise to avoid late-onset hypoglycemia." (PMID 34489869, 2021). "Compared with a conventional premixed insulin, twice-daily IDegAsp showed similar overall hypoglycemia risk and significantly lower risk of nocturnal hypoglycemia." (PMID 34564455, 2021). "Hypoglycaemia caused by glycogen storage/synthesis diseases, impaired gluconeogenesis or fatty acid oxidation is usually attributed to liver function, whereas hypoglycaemia due to insulin, GH or cortisol impairment is caused by endocrine dysfunction." (PMID 34750991, 2021). "On the other hand, glucose-free dialysate determines risk for hypoglycemia (especially in diabetic patients taking insulin) and greater amino acid losses due to induction of a catabolic state." (PMID 34395456, 2021). "In patients with hypoglycemia (sulfonylurea) and who are treated with insulin injections, drinking is a risk factor." (PMID 33915834, 2021). "Sensitivity analyses showed that the probability of using GLP-1RAs versus insulin being cost-effective for preventing one case of all-cause mortality or hospitalized hypoglycemia ranged from 60 to 100%." (PMID 33468131, 2021). "More recent insulin formulations are also associated with lower rates of hypoglycemia in T1DM and in some settings for T2DM." (PMID 33402217, 2021). "After the unannounced rapid rise in glucose at breakfast that continued at lunch, the system predicted a greater subsequent rise in glucose that increased aggressiveness of the insulin response, causing the observed hypoglycemia." (PMID 33931977, 2021). "In this research, n-hexane and ethyl acetate fractions of TO extract were used to investigate the cellular fate of glucose following hypoglycaemia caused by TO-mediated insulin increase." (PMID 33997754, 2021). "T1DM patients suffer from great risk of hypoglycemia due to exogenous injection of insulin and impaired glucagon and the adrenalin responses." (PMID 34819569, 2021). "Congenital hyperinsulinism (CHI), the major cause of persistent hypoglycemia in neonates and infants, is characterized by inappropriate insulin secretion from pancreatic beta cells in the presence of low blood glucose levels." (PMID 32482020, 2021).
Hypoglycemia (continued). "Hyperinsulinism (HI) due to excess and dysregulated insulin secretion is the most common cause of severe and recurrent hypoglycemia in childhood." (PMID 34435596, 2021). "When intensifying treatment, there is also an increased risk of hypoglycemia especially as add-on therapy to insulin or sulphonylurea." (PMID 36994321, 2021). "Can the risk of iatrogenic hypoglycemia resulting from insulin or insulin secretagogues be predicted continuously throughout hospitalization without the use of continuous glucose monitors?" (PMID 33416883, 2021). "In our study, the cohort in P4P had a slightly higher percentage of insulin therapy, which was a risk factor for hypoglycemia and associated mortality." (PMID 33478477, 2021). "In type 2 diabetic patients, both insulin deprivation and duration of insulin treatment increase the risk of hypoglycemia." (PMID 34067715, 2021). "Effective insulin management using an insulin pen helps patients improve adherence, facilitate self-management of people with DM, prevent the risk of hypoglycemia, and improve the quality of life." (PMID 34497858, 2021). "Long-acting insulin analogues were developed to reduce the risk of hypoglycaemia, especially nocturnal hypoglycaemia, producing greater patient convenience through reducing the number of injections." (PMID 35095504, 2021). "In December 2019, she was admitted to emergency room because of another severe hypoglycemia with loss of consciousness due to inappropriate insulin administration." (PMID 33864123, 2021). "Patients with T1DM, due to intensive insulin therapy, are usually associated with a higher risk of hypoglycemia and in our study 85.7% of T1DM vs only 40.4% of T2DM had a hypoglycemic episode in previous 12 months." (PMID 33402217, 2021). "Specifically, insulin (both prandial and basal) and sulfonylureas (including the short-acting meglitinides) are associated with a high risk of hypoglycemia." (PMID 34067055, 2021). "Intensive insulin therapy has been shown to be associated with an increased risk of hypoglycaemia in the critical care setting." (PMID 34277991, 2021). "Duration and intensity of exercise influence the risk of hypoglycemia, partly because of an increased insulin sensitivity after exercise." (PMID 34512541, 2021). "Although a substantial number of T2D Medicare beneficiaries are treated with less-intensive insulin regimens, they are at much higher risk for severe hypoglycemia than younger patients." (PMID 33844588, 2021). "ACE inhibitors are responsible for temporarily increasing the sensitivity to insulin, leading to a higher risk of hypoglycemia when associated with sulphonylureas." (PMID 34946233, 2021). "Whenever possible, stepwise addition of bolus insulin is preferred over full basal-bolus therapy in people with T2DM to reduce the risk of hypoglycemia, patient dropouts, and improved patient satisfaction." (PMID 34071359, 2021). "A randomized controlled trial among T2DM patients also concluded that insulin degludec improved glycemic control similarly to insulin glargine with a lower risk of hypoglycemia." (PMID 34345540, 2021). "Regarding the side effects of antidiabetic treatment, CKD increases the risk of metformin-associated lactic acidosis and hypoglycemia induced by insulin-secreting drugs when kidneys are involved in their metabolism." (PMID 34946320, 2021). "The reduced magnitude of glucose levels following administration of the co‐formulation is an unexpected, but advantageous, effect since it combines coverage of mealtime glucose spikes with a reduced risk of insulin stacking or post‐prandial hypoglycemia." (PMID 34499434, 2021). "SGLT2is inherently present a low risk of hypoglycemia because of their insulin-independent pathway of action." (PMID 34068655, 2021).
Hypoglycemia (continued). "The intensification of diabetic therapy after metformin, such as additional OADs or insulin, depends on individual characteristics including life expectancy, comorbidities, age, provider and patient's preferences, and the risk of hypoglycemia." (PMID 34457016, 2021). "We evaluated the effect of the insulin application methods on glycemic control, risk of hypoglycemia, adherence to treatment and impact on quality of life." (PMID 34118981, 2021). "Known risk factors for hypoglycemia in postbariatric patients are younger age, female gender, greater postoperative loss of weight, and pre-operative high insulin sensitivity." (PMID 33624213, 2021). "Insulin‐induced hypoglycemia is associated with an epinephrine‐driven rise in muscle glycogen breakdown resulting in increased muscle lactate production and a rise in blood lactate." (PMID 33769710, 2021). "The role of neural regulation of blood glucose level is particularly evident in hypoglycemia-associated autonomic failure in diabetes, a serious threat to diabetic patients with insulin treatment." (PMID 34354571, 2021). "Nevertheless, insulin therapy is often necessary to achieve satisfactory glycemic control thereby increasing the risk of hypoglycemia." (PMID 34085953, 2021). "Among insulin users, hypoglycemia, coping with the risk of hypoglycemia and other associated worries were highlighted as major negative psychological impacts." (PMID 34507618, 2021). "The risk of hypoglycemia which is a significant concern with insulin, is negligible with the intranasal route." (PMID 34540446, 2021). "As hypoglycemia is associated with a risk of unconsciousness, seizure, arrhythmia, and death, constant plasma Glc level monitoring along with adjustment of insulin infusion must be performed at all times." (PMID 34484102, 2021). "In the present study, we chose to include insulin-treated patients with an HbA1c ≤ 7.5% to ensure a population with high risk of hypoglycemia." (PMID 34952579, 2021). "These analyses were repeated after stratifying by baseline use of drugs associated with hypoglycaemia (insulin and sulphonylureas)." (PMID 35602215, 2021). "The mean rate of glycemia increase we found was similar to that caused by insulin-triggered hypoglycemia." (PMID 34836420, 2021). "Short-acting analogues (Lispro and Aspart) have faster onset and shorter duration of action determining a more overlapping peak to the one of the endogenous insulin, reducing the risk of post-meal hypoglycemia and improving glycemic control in women with GDM." (PMID 33767671, 2021). "SMBG should be performed using capillary blood, and the number of tests required to adequately monitor blood glucose levels depends on several factors: diet, physical activity, type of treatment (diet/insulin), and the risk of hypoglycemia." (PMID 34840988, 2021). "They reduced their basal insulin before exercise to reduce the risk of hypoglycemia during the workout." (PMID 36994325, 2021). "In particular, in this study, T1DM patients treated with insulin Degludec compared with those using Glargine U100, had a reduced risk of overall symptomatic hypoglycemia." (PMID 34572493, 2021). "This increasingly includes greater use of long-acting insulin analogues, which were developed to reduce the risk of hypoglycaemia, especially nocturnal hypoglycaemia, and provide greater convenience for patients with a reduced number of injections." (PMID 34249838, 2021). "In the present study, it’s worth noting that S1P-induced insulin secretion is glucose-dependent, which imply a reduced risk of hypoglycemia." (PMID 34322019, 2021). "Its advantages include insignificant risks of clinical hypoglycemia, which is a serious side effect caused by antidiabetic agents such as insulin and sulfonylureas." (PMID 34200427, 2021). "This reflects the safety profile of long-acting IDeg, which provides continuous, slow, and stable basal insulin coverage, thereby reducing the risk of hypoglycemia." (PMID 34564455, 2021).